SPARC (secreted protein acidic and cysteine rich)
Diseases named in the same sentence as SPARC in open-access papers (continued):
Sharing a sentence is not in itself a finding about the gene and the disease.
cancer (continued). "We show the effect of SPARC on activation of the main TFs orchestrating inflammation, adipocyte dysfunction, and cancer progression." (PMID 30765860, 2019). "We also reported that SPARC normalizes the TME through anti-inflammatory properties through suppression of the bi-directional cross-talk between cancer cells and macrophages and mesothelial cells." (PMID 30765860, 2019). "In this study, we show that SPARC serves as a modulator of ER stress: in cancer cells with an abundance of SPARC, this protein lowers the threshold of ER stress signaling activation by interfering with the binding between GRP78 and stress sensors." (PMID 31243264, 2019). "In contrast to the fibrosis-promoting SPARC function, the roles of stromal SPARC in human carcinomas appear to be far more complex and even contradictory according to previous reports." (PMID 31067787, 2019). "Nab-paclitaxel has shown antitumor activity in different malignancies that overexpress the albumin-binding protein SPARC, including cancers of the breast, lung, and skin." (PMID 29623263, 2018). "Our study shined the light on novel paracrine functions of SPARC-suppressing OvCa through metabolic programming and plasticity of cancer cells." (PMID 30332737, 2018). "A clearer description of the molecular mechanisms of SPARC action is needed to understand its divergent effects on human cancers." (PMID 28425924, 2017). "Secreted protein acidic and rich in cysteine (SPARC), an albumin-binding protein, is downregulated by hypermethylation in many cancers." (PMID 28881739, 2017). "In our study, we found that SPARC was up-regulated and promote cancer cell proliferation and migration via PCR, western-blot, immunohistochemical analysis, CCK-8 assay and wound healing assay." (PMID 29262657, 2017). "We try to identify a novel has-mir-29c-3p target gene, SPARC, which is involved in invasion and migration of colon cancer cells and further supports the role of mir-29c-3p in the inhibition of cancer in human cancers." (PMID 29262657, 2017). "The stromal cells close to the cancer nests expressed more SPARC than those far away from the cancer nests." (PMID 29156791, 2017). "SPARC (secreted protein acidic and rich in cysteine), a multicellular non-structural glycoprotein is known to be involved in multiple processes in various cancers." (PMID 28435518, 2017). "The distribution and the related function of SPARC in the stroma and cancer cells is an intriguing topic." (PMID 28053291, 2016). "SPARC staining was weak in cancer cells, while exhibited a relatively strong signal in the cytoplasm of surrounding stromal cells." (PMID 28053291, 2016). "In cancer stroma, SPARC regulates extracellular matrix (ECM) assembly, exhibits anti-adhesive function, and promotes emigration and invasion." (PMID 28053291, 2016). "In contrast, expression of these proteins was predominately found in the area of intratumoral stroma, apart from concordant immunostaining in cancer cells for SPARC." (PMID 27487140, 2016). "As the majority of mechanistic studies examining SPARC function during cancer metastasis have been conducted using in vitro cell culture models, it is not clear which, if any, of these mechanisms are relevant to SPARC’s pro-invasive function in vivo." (PMID 26926673, 2016). "SPARC, as a potential molecular marker of prognosis in malignant tumors, has generated remarkable interest in this crucial period of the high morbidity and mortality of malignancies." (PMID 26731428, 2016). "It was also noticed that SPARC expression was either statistically meaningless for the prediction of cancer differentiation or significantly related with better cancer differentiation in some previous studies in GC." (PMID 28053291, 2016). "Although this study is the first to demonstrate the role of OPN in prostate tumorigenesis, another SIBLINGs member, namely SPARC, has been shown to favor the occurrence of more aggressive cancers, of undefined histotype in TRAMP mice, if deleted." (PMID 26700622, 2016).
cancer (continued). "In human carcinogenesis, SPARC plays remarkable roles in altering the activity and the microenvironment of cancer cells, modulating cell growth, apoptosis, adhesion migration and invasion, regulating ECM and the activity of matrix metalloproteinases." (PMID 26731428, 2016). "Through modulation of cancer cells’ interactions with stromal cells, SPARC inhibited phenotypic commitment of macrophages and fibroblasts into inflammatory TAM and CAF phenotype." (PMID 27564266, 2016). "Among the 137 cancer specimens in the current study, 84 (61.3%) demonstrated high immunoactivity of SPARC." (PMID 28053291, 2016). "The SPARC signal in the ECM of carcinoma tissue had the lowest value in respect to that of all the other parameters." (PMID 26703564, 2015). "SPARC was found to be differentially expressed in tumors and its surrounding stroma in various types of cancers in comparison to normal tissue." (PMID 24535175, 2014). "Mouse as well as human pancreatic CTCs exhibit a very high expression of stromal-derived extracellular matrix (ECM) proteins, including SPARC, whose knockdown in cancer cells suppresses cell migration and invasiveness." (PMID 25242334, 2014). "Among those genes are IFNGR2, PITX2, RFWD2, PPARγ, LOXL2, Rab6 and SPARC, all involved in cancer-related pathways." (PMID 24875049, 2014). "In parallel, there is also substantial evidence that SPARC endogenously produced by cancer cells favors their invasive, survival and tumorigenic properties." (PMID 25331979, 2014). "In contrast, lower levels of SPARC expression have been found in other types of cancers, such as ovarian cancer, colorectal cancer, pancreatic cancer and acute myelogenous leukemia." (PMID 23516489, 2013). "SPARC is differently expressed in various cancers and in the surrounding stroma compared to normal tissues, and its expression pattern is variable and highly dependent on the type of cancer." (PMID 24396828, 2013). "A better understanding of the role of SPARC, for example, in cancer would improve certain biologically-based anti-cancer therapies." (PMID 23349702, 2013). "This is important to consider because the role of SPARC in cancer is somewhat controversial, as it positively correlates with invasion or worse prognosis for some cancers, but negatively correlates with invasion or worse prognosis for others." (PMID 22480225, 2012). "Depending on the cancer type, SPARC has been proposed both as a therapeutic target and as a therapeutic agent." (PMID 22480225, 2012). "SPARC is differentially expressed in tumors and its surrounding stroma in various cancers in comparison to the normal tissue." (PMID 22879971, 2012). "Secreted protein acidic and rich in cysteine (SPARC), a calcium-binding matricellular glycoprotein, is implicated in the progressions of some cancers." (PMID 23050783, 2012). "Another matricellular protein, whose multifaceted influence in cancer microenvironment has been progressively delineating, is SPARC." (PMID 22400028, 2012). "Secreted protein acidic and rich in cysteine (SPARC) is a glycoprotein that functions to inhibit angiogenesis, proliferation, and invasion in different types of cancer." (PMID 22957090, 2012). "The inhibition of SPARC expression diminishes tumorigenicity and metastatic dissemination of these cancer cells." (PMID 22481923, 2012). "Several matricellular proteins, such as SPARC, OPN, CCN1, CCN6, and TNC, have been implicated in either the promotion or suppression of EMT, highlighting their role in cancer progression and malignant behavior of cancer cells." (PMID 22481923, 2012). "SPARC-induced changes can suppress or promote progression of different cancers depending on the tissue and cell type." (PMID 24213109, 2011). "This is an area that requires further investigations, in order to allow a better understanding of SPARC's effect in different types of cancers." (PMID 22069448, 2011).
cancer (continued). "Further, the same group showed that SPARC produced by TAM enhances cancer cell migration and spontaneous metastasis, via a mechanism that involved avb5 integrin." (PMID 24213109, 2011). "SPARC expression was significantly greater in all cancer (stage II and III combined) compared to normal colonic tissue (p<0.0001), with no statistical differences detected in SPARC expression between patients with stage II and III disease." (PMID 21818290, 2011). "SPARC (secreted protein, acidic and rich in cysteine) is closely related with the progress, invasion and metastasis of malignant tumor and angiogenesis." (PMID 20565704, 2010). "Cancer cells treated with a SPARC antibody resulted in an abrogation of fenretinide-induced decrease in cell invasion." (PMID 20687958, 2010). "Yet, lower levels of SPARC expression have also been found in other types of cancers, such as ovarian and pancreatic." (PMID 20565704, 2010). "Overall, our results reveal a novel cooperative role of Brg-1 and Sp1 in mediating the constitutive and fenretinide-induced expression of SPARC, and provide new insights for the understanding of the anti-cancer effects of fenretinide." (PMID 20687958, 2010). "Overall, our results reveal a novel regulatory mechanism mediating the expression of SPARC and provide new insights for the understanding of the anti-cancer effects of fenretinide." (PMID 20687958, 2010). "In some types of cancer, high levels of SPARC expression have been shown to correlate with disease progression and poor prognosis." (PMID 20525313, 2010). "From a clinical point of view, IL1RN, MAL and TGM3 were not clearly identified as potential HNSCC markers, while few data have been published concerning the implication of FN1, KRT, MMP1, PLAU and SPARC in this type of cancer." (PMID 19835631, 2009). "The expression of SPARC was higher in advanced (T2, T3 and T4) cancer compared to the early (T1) cancer (P=0.048) with regard to depth of wall invasion." (PMID 15558074, 2004). "The Northern blot analysis determined the mean expression of SPARC in cancer tissues was 4.7-fold (range 1–12) greater than in their noncancerous counterpart, which confirmed the trend observed in the real-time Q-RT–PCR." (PMID 15558074, 2004). "In the group of patients with EA (EA group, n=20), 18 of 20 (90%) patients had higher SPARC mRNA expression levels in cancer tissues compared to matching NE tissues." (PMID 14562024, 2003). "Our findings complement the results of previous studies that reported alterations in SPARC expression in various human cancers." (PMID 14562024, 2003). "SPARC mRNA expression levels were significantly higher in normal squamous oesophagus tissues from patients with cancer compared to patients with the maximum diagnosis of BE and the CG without the evidence of BE or chronic gastro-oesophageal reflux." (PMID 14562024, 2003). "In histologically normal squamous oesophagus tissues obtained from carcinoma patients (EA group), the SPARC mRNA expression was significantly higher compared to NE mucosa from the BE group and the CG group (P=0.03)." (PMID 14562024, 2003). "The link between Caspase‐8 and Bcl‐2 may be disrupted by the SPARC peptide, which can restore sensitivity in chemoresistant cancers." (PMID 40415238, 2025). "Recently, the role of SPARC in cancer chemoresistance has received increasing attention." (PMID 40415238, 2025). "While SPARC promoter methylation is a frequent event in several cancers and may contribute to ECM dysregulation in both fibrotic and malignant settings, the extent to which this epigenetic mark confers increased cancer susceptibility in IPF remains unclear." (PMID 40970095, 2025). "SPARC, as a secreted protein, is thought to regulate the interaction between cells and the extracellular matrix and has powerful biological functions, especially in pathological conditions such as cancer." (PMID 40415238, 2025).
cancer (continued). "However, secretion of SPARC by cancer-associated fibroblasts (CAF) disrupts adhesion and increases the motility of TNBC in vitro, suggesting SPARC is favorable for disease progression." (PMID 40847127, 2025). "SPARC methylation status was analyzed using a specific primers/probe set targeting the CpG-rich region located at the promoter gene region, reported as mainly affected by a high variability of methylation density in cancer." (PMID 40970095, 2025). "LCN2 could affect EMT process by regulating MMP protein expression in GC, and a close relationship between MMP protein expression and SPARC expression has also been found in other cancers." (PMID 39424639, 2024). "Furthermore, albumin is one of the efficient biomimetic molecules with a cancer-targeting ability because it can bind the gp60 receptor and SPARC protein, which are overexpressed in several cancer cells." (PMID 39456987, 2024). "Unexpectedly, FAP and VIM were not as highly associated with SPARC expression in the cancer stroma of BC tumors and exhibited low expression." (PMID 39335478, 2024). "In addition, the genes coregulated by ZBTB11 and SET, such as MMP9 and SPARC, have been well validated to participate in the regulation of cancer cell migration and invasion." (PMID 38355937, 2024). "Survival maps of 32 types of cancer show that SPARC gene is a strong prognostic indicator for MESO." (PMID 37509139, 2023). "The utilization of therapeutic genes that are directed by the SPARC driver could be a useful approach for the treatment of cancer." (PMID 37577749, 2023). "SPARC is located in peritumoral fibroblasts and rarely observed in cancer cells’ cytoplasm." (PMID 37577749, 2023). "Based on this feature, SPARC is often used as a prognostic marker for different cancers." (PMID 37577749, 2023). "Besides, MCM3AP-AS1 was reported to be upregulated in PTC and it promotes proliferation and invasion of cancer cells through regulating the miR-211-5p/SPARC axis in PTC." (PMID 35929906, 2023). "The SPARC gene is found to be upregulated in a variety of cancer types, including MESO." (PMID 37509139, 2023). "In addition to the stimulatory effect of TGF-β1 on SPARC expression, Snail and Slug can also be upregulated by SPARC in human cancer cells." (PMID 37158892, 2023). "Many papers have demonstrated that serum albumins could specifically bind to 60 kDa glycoprotein (gp60) and SPARC (an acidic and cysteine-rich protein), determining its uptake into cancer cells via transcytosis." (PMID 37836018, 2023). "SPARC is a secreted protein that is overexpressed in multiple cancers, including GI cancers, and its overexpression may be associated with a positive response to nab-paclitaxel." (PMID 37509639, 2023). "SPARC is categorized as a promising target and indicator for treating various cancers." (PMID 37577749, 2023). "Due to the increased permeability and retention typical for the tumor, as well as the presence of specific receptors (Gp60, SPARC, FcRn) whose expression levels are increased in some cancers, albumin-binding constructs have great potential in cancer diagnosis and theranostics." (PMID 38140119, 2023). "SPARC over expression was observed in stromal tissues and epithelial cells in most cancers." (PMID 37509139, 2023). "Here, high SPARC-CAFs correlations were found for 18 cancer types." (PMID 36604669, 2023). "This second cluster could represent a cancer-associated fibroblast (CAF) population characterized by low expression of MSLN and WT1 and high expression of ACTA2, S100A4, COL5A2, SPARC, and FN1." (PMID 36901697, 2023). "Depending on the cancer type, the expression of Snail, Slug, or both can be upregulated by SPARC." (PMID 37158892, 2023). "By affecting the extracellular matrix composition SPARC can potentially affect cancer growth." (PMID 35917053, 2022). "Several integrins are mediators of SPARC effects in cancer cells." (PMID 35682554, 2022).
cancer (continued). "From our big data studies validated with independent datasets, protein-coding hub genes FN1, CD44, TIMP1, SNAI2, and SPARC were found significantly enriched in signal transduction, proteolysis, cell adhesion and proteoglycans pathways in cancer as well as the PI3K/Akt-signaling pathway." (PMID 35534592, 2022). "An abnormal expression of SPARC proteins is found in human pathologies such as chronic inflammation, fibrosis, rheumatoid arthritis, kidney diseases, diabetes, central nervous system diseases, cancer and cancer metastasis." (PMID 36506087, 2022). "SPARC is involved in regulating multiple cancers progression as a target gene of miR-211." (PMID 35912006, 2022). "Moreover, it is known that AMPK can directly activate the secreted protein acidic and rich in cysteine (SPARC), a matricellular protein that supports glucose metabolism in adjacent cancer cells." (PMID 34606156, 2022). "However, in the case of combined Selumetinib- and Trametinib-resistant cancers, FN1 and CD44 were down-regulated; TIMP1 and SNAI2 were down-regulated only in Selumetinib-resistant ones; while SPARC was down-regulated in the case of Trametinib-resistant cancer." (PMID 35534592, 2022). "The loss of E-cadherin expression disrupts this complex resulting in the loss of cell polarity, epithelial denudation, and increased epithelial permeability in a variety of tissues, promoting cancer cell migration, invasion, and metastasis events that are also induced by SPARC in PCa cells." (PMID 35682554, 2022). "Further, SPARC is involved in a process known as cell competition, that is, a cell–cell interaction phenomenon, originally discovered in D. melanogaster and described also in human cancers, resulting in a ‘battle’ of cells with different fitness." (PMID 34606156, 2022). "Besides its involvement in cancer, the function of SPARC in inflammation has been demonstrated in earlier studies." (PMID 33920268, 2021). "Moreover, various albumin receptors, namely, gp60 and SPARC, are overexpressed in cancer cells, which can contribute to enhance further the uptake of albumin-based cargos in the cancer sites." (PMID 34208533, 2021). "In addition to functions in cancer cells, SPARC also plays a critical role in stromal cells in in cancer progression." (PMID 33579227, 2021). "From this analysis, we noted that multiple elevated transcripts within the extracellular matrix organization GO term, particularly, CD44, osteopontin (SPP1), SPARC, and integrin A3 (ITGA3), have been widely studied in GBM and implicated with cancer invasion/metastasis and severity." (PMID 33843470, 2021). "In some cases, SPARC expression was exclusive in some part of the cancer tissue." (PMID 33579227, 2021). "Previous studies reported that FL SPARC and particularly its C-terminal extracellular Ca2+ binding domain can modulate adhesion, spreading, motility, endothelial transmigration, and invasion of cancer and stromal cells 25, 26, 33, 47-49." (PMID 33995652, 2021). "SPARC can be produced by both cancer cells and cells that form the TME." (PMID 34209679, 2021). "In addition to the expression of SPARC in cancer cells, its expression in stromal cells also plays a critical role in cancer progression." (PMID 33579227, 2021). "The secreted protein acidic and rich in cysteine (SPARC) was originally identified as a collagen-binding glycoprotein and it is involved in many biological processes, including tissue remodeling, angiogenesis, and cancer cell differentiation and migration." (PMID 34199373, 2021). "Moreover, SPARC binds to albumin and co-localizes as a bound form in cancer tissues, and its expression is correlated with improved survival in several cancers." (PMID 34141613, 2021). "In cancer, SPARC is mainly secreted by the neighboring stroma, but also by cancer cells 26-28." (PMID 33995652, 2021).